INO80 (INO80 complex ATPase subunit)
Diseases named in the same sentence as INO80 in open-access papers (continued):
Sharing a sentence is not in itself a finding about the gene and the disease.
colon cancer (4 papers, 2017 to 2023). "Our exploration of the mechanism underlying this effect suggested that Ino80 haploinsufficiency inhibited colon cancer tumorigenesis by activating replication stress-induced ATR-Chk1 signaling to increase apoptosis." (PMID 29383140, 2017). "We next determined the expression level of Ino80 and several associated subunits in normal colon cells and a variety of colon cancer cells." (PMID 29383140, 2017). "Here, we show that a haploinsufficient mutation of Ino80, the catalytic ATPase of the INO80 complex, decreased intestinal adenomatous polyps and increased survival in an Apcmin/+ mouse model of colon cancer." (PMID 29383140, 2017). "The target relationship between miR-372 and INO80 complex was verified using luciferase assays in HCT116 colon cancer cells." (PMID 37445863, 2023). "In the present study, we investigated the impact of INO80 on tumorigenesis using colon cancer as a model case." (PMID 29383140, 2017). "Whereas we had originally predicted that INO80 would function as a tumor suppressor, we found that INO80 actually acted oncogenically in colon cancer tumorigenesis in that Ino80 haploinsufficiency inhibited intestinal tumors in the Apcmin/+ mice." (PMID 29383140, 2017). "Strikingly, we found that the levels of all of the INO80 subunits that were analyzed were higher in the colon cancer cells than in normal colon cells." (PMID 29383140, 2017). "To study the mechanism involved in this process, we used tumors obtained from Apcmin/+ mice and human colon cancer cells and showed that a deficit in Ino80 induced replication stress, leading to the ATR-mediated activation of Chk1 and increased apoptosis." (PMID 29383140, 2017). "Importantly, in human colon cancers, INO80 subunits had a high frequency of gaining copy numbers and a high rate of amplification and there was an increase in the protein expression levels of these markers." (PMID 29383140, 2017). "Finally, we also found that INO80 is upregulated in human colon cancer, indicating that our findings have clinical significance." (PMID 29383140, 2017). "INO80 therefore represents a novel therapeutic target in colon cancer." (PMID 29383140, 2017). "Furthermore, an analysis performed using a tissue microarray showed that the expression level of Ino80 was significantly higher in colon cancers than in normal colon tissues." (PMID 29383140, 2017). "To determine whether INO80 is involved in colon cancer tumorigenesis, we crossbred Ino80+/− mice with Apcmin/+ mice and analyzed the intestinal polyps of the resulting offspring at the age of 100 days." (PMID 29383140, 2017). "Because we found that Ino80 depletion induced stalled replication forks, we next asked whether Ino80 activates ATR-Chk1 signaling in human colon cancer cells." (PMID 29383140, 2017). "We therefore used DNA fiber-labeling assays to determine whether INO80 performs these functions in human colon cancer cells." (PMID 29383140, 2017). "Importantly, in human colon cancer, we observed that the INO80 subunits were frequently present in high copy numbers and exhibited a high rate of amplification and increased protein expression." (PMID 29383140, 2017). "Here, we investigated whether INO80 is directly involved in tumorigenesis in colon cancer." (PMID 29383140, 2017). "Therefore, we concluded that knocking down Ino80 increases apoptosis in human colon cancer cells." (PMID 29383140, 2017). "INO80 occupancy affects replication forks, and its silencing can activate the replication stress-induced ATR-CHK1 signaling pathway in colon cancer." (PMID 38020889, 2023). "Therefore, we sought to determine whether INO80 is upregulated in human colon cancer." (PMID 29383140, 2017). "Knocking down Ino80 using siRNA decreased the track length of ongoing forks in both HT29 and SW480 cells, indicating that as in HeLa and PC cells, INO80 plays a role in normal replication fork progression in colon cancer cells." (PMID 29383140, 2017).
microcephaly (4 papers, 2020 to 2023). A congenital or acquired developmental disorder in which the circumference of the head is smaller than normal for the person's age and sex. "The loss of INO80 results in microcephaly due to unrepaired DNA breaks and increased apoptosis in neural progenitor cells undergoing symmetrical divisions." (PMID 36831199, 2023). "Loss of Ino80 in NPCs (Neurod6Cre/+;Ino80fl/fl) impairs these processes, causing apoptosis and microcephaly in mice." (PMID 33263776, 2021). "While this loss of progenitor cells during development could explain microcephaly due to the loss of INO80, whether and how this affects the development of the inner ear and hearing function is not yet known." (PMID 36831199, 2023). "The INO80 gene was identified as another candidate for microcephaly and it has been shown to play a role in the HR pathway, mediating the removal of histone subunit H2A.Z, and exchanging RPA for RAD51, which are crucial steps in the DSB repair." (PMID 37881689, 2023). "In correspondence with these findings, INO80 was recently identified as a candidate gene for ID and microcephaly." (PMID 33263776, 2021). "Analyzed at P0, Brca2 deletion by Emx1Cre (Emx1Cre/+;Brca2fl/fl, Brca2 cKO-E) led to significant microcephaly, callosal agenesis, and hippocampal hypoplasia remarkably similar to Ino80 cKO-E." (PMID 32737294, 2020). "Our data thus strongly support Ino80 cKO apoptosis and microcephaly as consequences of impaired DNA repair." (PMID 32737294, 2020). "An earlier study investigating neurogenetic disorders reported microcephaly and developmental delay in patients with mutations in INO80, although hearing loss was not reported." (PMID 36831199, 2023). "INO80 was recently identified as a candidate gene for microcephaly and intellectual disability." (PMID 32737294, 2020).
non-small cell lung carcinoma (4 papers, 2017 to 2025). A group of at least three distinct histological types of lung cancer, including non-small cell squamous cell carcinoma, adenocarcinoma, and large cell carcinoma. "In non-small cell lung cancer, INO80 has been demonstrated to play a critical role in promoting oncogenic transcription and tumorigenesis." (PMID 40541951, 2025). "For instance, alterations in the INO80 complex were found in approximately 80% of non-small-cell lung carcinomas (PanCancer Atlas), and in approximately 60% of breast, lung, and colorectal cancers (PanCancer Atlas)." (PMID 38020889, 2023).
prostate carcinoma (4 papers, 2017 to 2023). A carcinoma that arises from epithelial cells of the prostate gland. "It was shown recently that the ATP‐dependent chromatin remodeling INO80 (INO80 Complex ATPase Subunit) complex promotes resolution of R‐loops to prevent replication‐associated DNA damage in cancer cells, while depletion of INO80 in prostate cancer cells leads to increased R‐loops." (PMID 37042179, 2023). "Depletion of INO80 in prostate cancer PC3 cells leads to increased R-loops." (PMID 32913330, 2020). "Chromatin remodeling complexes, such as the one of Mec1, INO80 and PAF1 in budding yeast, can prevent TRC by removing RNAPII; INO80 depletion in prostate cancer cells leads to increased formation of R-loops." (PMID 33918762, 2021). "By using oncogene-driven prostate cancer PC3 cells, we find that INO80 prevents replication stress-induced DNA damage and promotes proper and efficient DNA synthesis by counteracting accumulation of R-loops." (PMID 32913330, 2020).
colorectal cancer (3 papers, 2023 to 2025). A primary or metastatic malignant neoplasm that affects the colon or rectum. "ACTL6A (also known as BAF53A and INO80K) is a shared subunit of the SWI/SNF and INO80 complexes and functions as a driver of colorectal cancer (CRC), glioma, squamous cell carcinoma (SCC), hepatocellular carcinoma." (PMID 40877226, 2025). "ACTL6A, a subunit of the SWI/SNF and INO80 chromatin remodeling complexes, is frequently overexpressed in various cancers, and its depletion attenuates cell proliferation in colorectal cancer (CRC)." (PMID 40877226, 2025). "In this report, we first proposed that the INO80 complex and miR-372 are mutually regulated in HCT116 colorectal cancer cells using in vitro biological experiments combining knockdown and over-expression approaches." (PMID 37445863, 2023).
lymphoma (3 papers, 2016 to 2022). A malignant (clonal) proliferation of B- lymphocytes or T- lymphocytes which involves the lymph nodes, bone marrow and/or extranodal sites. "Hepatosplenic T-cell lymphoma (HSTL) is a rare and fatal lymphoma, and INO80 mutation was found to be predominant in HSTL with a high mutation rate (21%)." (PMID 36361605, 2022).
osteoporosis (3 papers, 2016 to 2025). A condition of reduced bone mass, with decreased cortical thickness and a decrease in the number and size of the trabeculae of cancellous bone (but normal chemical composition), resulting in increased fracture incidence. "This discovery suggests that INO80 is not only important for normal bone formation but also contributes to osteoporosis development." (PMID 40696462, 2025). "As to osteoporosis, the INO80 chromatin remodeling complex interacts with WD repeat-containing protein 5 (Wdr5) protein that catalyzes H3K4me3 formation to positively regulate the canonical Wnt pathway." (PMID 32963550, 2020). "Correspondingly, after INO80 gene is knocked down, the osteogenic potential of MSCs decreases both in in vitro and in ectopic transplantation models, reproducing a similar phenotype as osteoporosis." (PMID 32963550, 2020). "Moreover, INO80 can be presented as a new avenue to study MSC-related aging and osteoporosis in vivo." (PMID 27804957, 2016).
congenital heart disease (2 papers, 2018 to 2021). A heart disease that is present at birth. "Ino80 endothelial-deficient hearts develop congenital heart diseases due to disrupted coronary angiogenesis." (PMID 33430144, 2021). "Endothelial-specific deletion of Ino80 severely stunted coronary angiogenesis, which correlated with a dramatic decrease in the size of the compact heart wall and a phenotype reminiscent of the human congenital heart disease, LVNC." (PMID 29371594, 2018).
mesothelioma (2 papers, 2017 to 2023). A usually malignant and aggressive neoplasm of the mesothelium which is often associated with exposure to asbestos. "Importantly, Ino80 levels are often reduced in BAP1-null mesothelioma cells, which lack a BAP1-mediated Ino80 stabilization mechanism, and downregulated in BAP1-defective cancer cells in mesothelioma patients." (PMID 29383140, 2017).
Miscarriage (2 papers, 2021 to 2022). A pregnancy that ends at a stage in which the fetus is incapable of surviving on its own, defined as the spontaneous loss of a fetus before the 22th week of pregnancy. "Ino80 represses the expression of trophoblastic invasion-related genes during trophoblast development, and recurrent miscarriages can occur when Ino80 is suppressed." (PMID 36499727, 2022). "Collectively, our results indicated a potential role for decreased expression of the INO80 chromatin remodelling complex in the occurrence of miscarriage." (PMID 33724648, 2021). "Taken together, these results point to a pivotal role for Ino80 in regulating trophoblast migration and invasion, and the occurrence of miscarriage." (PMID 33724648, 2021).
postmenopausal osteoporosis (2 papers, 2025 to 2026). Metabolic disorder associated with fractures of the femoral neck, vertebrae, and distal forearm. "Future research plan to further explore the role of miR-370-3p/INO80 in postmenopausal osteoporosis by constructing an OVX animal model." (PMID 40696462, 2025).
Alzheimer disease (1 paper, 2019). A progressive, neurodegenerative disease characterized by loss of function and death of nerve cells in several areas of the brain leading to loss of cognitive function such as memory and language. "Additionally, INO80, Proteasome, and RNAPII machinery have also been shown to be associated with Alzheimer’s disease, potentially via RNAPII degradation by INO80." (PMID 31133796, 2019).
chronic kidney disease (1 paper, 2014). Impairment of the renal function secondary to chronic kidney damage persisting for three or more months. "Recently, an association was found between the SNPs in the INO80 gene and chronic kidney disease (CKD), an important public health problem with a genetic component." (PMID 25299602, 2014).
grange syndrome (1 paper, 2023). Grange syndrome is characterized by stenosis or occlusion of multiple arteries (including the renal, cerebral and abdominal vessels), hypertension, brachysyndactyly, syndactyly, increased bone fragility, and learning difficulties or borderline intellectual deficit. "The phenotypic overlap of the SMDS and Grange syndrome patients, along with the data presented here and loss of differentiation in mouse models with deficiency of BRG1, leads us to hypothesize that INO80 and BAF chromatin remodeling complex function is critical for SMC fate determination." (PMID 36909460, 2023).
hypospadias (1 paper, 2025). Hypospadias is the displacement of the urethral meatus on the ventrum of the penis. "INO80 encodes a chromatin remodelling factor that regulates Bone Morphogenetic Protein 4 (BMP4) expression, a well-established gene involved in urethral development and hypospadias pathogenesis." (PMID 41300791, 2025). "For instance, if genes such as INO80 and BMP4 are involved in the pathogenesis of hypospadias, therapeutic strategies that target chromatin remodelling or BMP4 signalling could be explored." (PMID 41300791, 2025).
intestinal tumors (1 paper, 2017). "It should be noted that because INO80 is known to play a role in transcription regulation, it remains possible that Ino80 deficiency also inhibits intestinal tumors in Apcmin/+ mice in part by inducing the dysregulation of gene expression." (PMID 29383140, 2017). "Our data suggest that Ino80 insufficiency inhibited intestinal tumors in Apcmin/+ mice by increasing the replication stress-induced activation of ATR-Chk1 signaling and thereby increasing apoptosis." (PMID 29383140, 2017). "We stained intestinal tumors obtained from Ino80+/+Apcmin/+ and Ino80+/−Apcmin/+ mice using antibodies against phopsho-Chk1-Ser-317 or phospho-Chk1-Ser-345." (PMID 29383140, 2017). "We next sought to determine the mechanisms by which the reduction in Ino80 increased apoptosis in the intestinal tumors of Apcmin/+ mice." (PMID 29383140, 2017). "Next, we sought to determine whether Chk1 is activated at a higher rate when Ino80 is reduced in intestinal tumors in Apcmin/+ mice." (PMID 29383140, 2017). "However, this is unlikely to be the case in intestinal tumors in Apcmin/+ mice because our data show that tumor cell proliferation was not affected by Ino80 deficiency." (PMID 29383140, 2017).
polyp (1 paper, 2017). A usually exophytic mass attached to the underlying tissue by a broad base or a thin stalk. "An analysis of polyp size showed that a large portion of the polyps in the small intestine was 1–2 mm in diameter and their frequency was not significantly different between the Ino80+/+Apcmin/+ and Ino80+/−Apcmin/+ mice." (PMID 29383140, 2017).